EGFR (epidermal growth factor receptor)
Diseases named in the same sentence as EGFR in open-access papers (continued):
Sharing a sentence is not in itself a finding about the gene and the disease.
tumor (continued). "A well-documented obstacle to improved patient survival is the presence of EGFR-inhibitor resistant tumor cell variants within heterogeneous tumor cell masses." (PMID 24349829, 2013). "EGFR tyrosine inhibitors are typically used to sensitize EGFR mutated tumor types to platinum agents, however EGFR wild-type tumors rarely response to these inhibitors." (PMID 24367505, 2013). "Due to its important contributions to tumour cell survival, proliferation, and motility, EGFR has been associated with many human malignancies, such as breast cancer, lung cancer, brain cancer, prostate cancer, and liver cancer." (PMID 24376686, 2013). "The quality of tumor biopsies sent in for mutational analysis was assessed and mutation status was related to treatment with EGFR TKI outcome." (PMID 23922984, 2013). "In our analyses, however, none of the baseline clinical factors was identified to be significantly associated with PFS and OS, with the exception of tumor response to TKIs, performance status and subtype of EGFR mutation." (PMID 24376677, 2013). "Aberrant activation of Raf-MEK-ERK and PI3K-Akt pathways driven by epidermal growth factor receptor (EGFR) is commonly observed and implicated in the tumor growth and progression of many human cancer types, including HCC." (PMID 23840262, 2013). "EGFR is of specific interest as the tumor-specific constitutively active variant III is associated with CD44+/CD24− subpopulation of breast CSCs33." (PMID 23982413, 2013). "The mean tumor size of the EGFR-mutated adenocarcinomas was significantly larger in males compared with females (P=0.027)." (PMID 24179496, 2013). "It is well recognized that matrix metalloproteinase-9 (MMP9), which is closely associated with tumor invasion and metastasis in several human tumors, can be inhibited by EGFR signaling pathway blockade." (PMID 23496982, 2013). "The overexpression of EGFR in tumors has been linked to poor prognosis due to its association with tumor progression, angiogenesis, migration, and metastasis." (PMID 23407898, 2013). "Because of limitations of tumor tissue sample for Cases 2 and 3, evaluation of EGFR mutation status was focused on exon 19 deletion." (PMID 24171005, 2013). "The EGFR mutation detection rate was 10%, taking into consideration the tested cytological samples with a minimum of 1,000 tumor cells." (PMID 23817662, 2013). "A similar detection rate was observed in tumor samples from primary and metastatic locations thus confirming the same distribution of EGFR mutations within the primary tumor and between primary tumor and metastases that are still matters of debate." (PMID 23497146, 2013). "Together this demonstrates that the rapid degradation of activated EGFR in AnxA6-depleted invasive tumor cells underlies their sensitivity to EGFR-targeted TKIs and reduced motility." (PMID 24354805, 2013). "Epidermal growth factor receptor (EGFR), a member of the receptor tyrosine kinase superfamily that is overexpressed in different types of cancers, is associated with tumor malignancy." (PMID 23774942, 2013). "These mutations have been shown to promote the activation of EGFR signaling and tumor dependency on EGFR." (PMID 24386407, 2013). "In the present study, we analyzed the association of tumor p16 expression with prognosis in a retrospectively collected cohort of patients with HNSCC treated with RT+EGFR inhibitors or RT+CT." (PMID 23331666, 2013). "Increased VEGF expression has been associated with resistance to EGFR inhibition in a human tumor xenograft model of NSCLC." (PMID 24124611, 2013). "EGFR mutations of surgically resected fresh tumor samples from 697 Chinese NSCLC patients were analyzed by Amplification Refractory Mutation System (ARMS)." (PMID 24351833, 2013). "Since the DNA was obtained from stored FFPE and the amount of DNA from tumor tissue was small, the EGFR mutational status of cohort B was tested with direct sequencing and PNA-LNA PCR clamp." (PMID 24376508, 2013).
tumor (continued). "In the Caucasian population, the percentage of patients with EGFR mutations in NSCLC primary tumours is lower compared with Asian patients (approximately 10–16 %)." (PMID 23892415, 2013). "In one additional case (case 57) the R831H mutation associated with resistance to TKIs was identified in a tumor that was EGFR wild type after the Sanger method." (PMID 24376723, 2013). "In order to better characterize intratumoral heterogeneity of EGFR, we microdissected bulk tumor tissue to obtain 28–34 foci per tumor and analyzed each focus for EGFR mutation status using qualitative and semi-quantitative methods." (PMID 23418425, 2013). "Recently, IgA variants of the chimeric IgG1 EGFR antibody cetuximab were generated and were shown to mediate efficient tumour lysis in vitro using human effector cells." (PMID 23918228, 2013). "The overexpression of EGFR exon 18 in tumor was significantly associated with tumor shrinkage, independently of EGFR mutation status." (PMID 24039832, 2013). "We developed assays aiming at accurately detecting EGFR mutations in patient tumor samples in routine screening." (PMID 23934203, 2013). "The detection of EGFR mutations in tumor tissues has been applied for predicting the response of TKI treatment and hence guiding the treatment for advanced NSCLC." (PMID 23340652, 2013). "To evaluate the accuracy of the results of the PNA test, we compared plasma EGFR mutations with tumor sequencing in 40 paired donor-matched plasma and tumor tissue specimens." (PMID 23927790, 2013). "One of the roles of Mig-6 is as a tumor suppressor gene, and in accordance with the well-established involvement of EGFR signaling in oncogenic progression, mice with global Mig-6 loss experience widespread and precocious tumor development." (PMID 23705804, 2013). "Each tumor sample was microdissected to yield 28–34 tumor foci and Intratumoral EGFR mutation were determined using Denaturing High Performance Liquid Chromatography (DHPLC) and Amplification Refractory Mutation System (ARMS)." (PMID 23418425, 2013). "The significant association between survival with EGFR GCN, revealed tumor growth is probably mainly driven by the EGFR pathway and this biological characteristic is evoked by an increase in EGFR copy number." (PMID 23441167, 2013). "Tumor tissue is the best choice for EGFR mutation analysis and these enable the microdissection of tumor cells." (PMID 23621919, 2013). "Genome-wide profiling and additional investigations revealed that high EGFR mRNA expression and immunohistochemistry score (3+) are associated with tumor growth inhibition." (PMID 24141978, 2013). "In such study ALI should be compared with tumor specific mutations like EGFR, KRAS, EML4-ALK etc. to see which mutations are associated with higher systemic inflammation." (PMID 23530866, 2013). "The association between high Mig6/EGFR ratio and erlotinib resistance suggests that tumor cells that have low EGFR activity will be largely unresponsive to EGFR TKIs." (PMID 23935914, 2013). "Together, this demonstrates that the rapid degradation of activated EGFR in AnxA6-depleted invasive tumor cells underlies their sensitivity to EGFR-targeted TKIs and attenuated motility." (PMID 24354805, 2013). "HER-2 can be heralded as a prognostic factor, as higher levels of this EGFR in serum seem to be associated with more severe disease; lymph node involvement, distant metastasis, increased tumor size and higher TNM stages of SCC." (PMID 24303437, 2013). "Among NSCLC patients with activating EGFR mutation, approximately 70% will experience significant tumor regressions when treated with an EGFR TKI." (PMID 22970367, 2012). "Several preclinical studies on cell lines from different tumour types, indicated that the association between EGFR/HER2 mAbs with TKIs displays an increased efficacy." (PMID 23234355, 2012). "P/AON/2C5/TfR, where two mAbs were combined, caused the highest inhibition of EGFR expression in the tumor." (PMID 22355336, 2012).
tumor (continued). "In our case, DNA sequencing of the EGFR gene in a tumor biopsy specimen at relapse showed a second point mutation that changed threonine to methionine at position 790 (T790M) of EGFR." (PMID 23144692, 2012). "Patients with a tumour harbouring a KRAS codon 12 or 13 mutation are resistant to anti-EGFR therapy." (PMID 22804917, 2012). "Direct sequencing was only able to detect the presence of an EGFR mutation in one of the tumours analyzed when mutant DNA represented 10% of the total DNA." (PMID 22952784, 2012). "EGFR mutations were significantly more often observed in ADC than in SCC or other tumor types (10.6 %, 0 %, and 4.3 % respectively, p = 0.006) and more frequently in female than in male patients (13.4 % vs. 5.5 %, p < 0.001)." (PMID 22528563, 2012). "Among patients with an EGFR activating mutation, approximately 70% of them will experience significant tumor regressions when treated with an EGFR TKI." (PMID 22970367, 2012). "These in vivo results are consistent with our in vitro results showing a potent induced effect of fucoxanthin on the apoptosis of tumor, which is associated with EGFR/STAT3 signal pathway." (PMID 23118721, 2012). "For example, overexpression of the EGFR agonist transforming growth factor alpha (TGFα) in mice causes hepatic hyperplasia and tumour formation, and EGFR is upregulated in a majority of human hepatocarcinomas." (PMID 22967907, 2012). "We also tested the effect of UDG treatment on detection of non-G>A changes i.e. in-frame deletions and insertion mutations using six NSCLC tumours harbouring either EGFR exon 19 or 20 mutations." (PMID 22643842, 2012). "We also reviewed available data on EGFR mutation in the tumor tissues of young patients and analyzed the relationship between EGFR mutation and EGFR-TKI treatment efficacy." (PMID 22695392, 2012). "ERBB3 is gaining attention because of its recently appreciated role in the resistance of tumor cells to EGFR/ERBB2-targeted therapies." (PMID 23691449, 2012). "Research attention has recently focused on EGFR gene polymorphisms, present in both skin and tumor tissues." (PMID 22997576, 2012). "Statistical analysis showed significant association between all EGFR immunohistochemical staining categories and percentage of positive tumor cells with chromosome 7 polysomy." (PMID 22475688, 2012). "Several publications reported up to 90% sensitivity for detection of EGFR mutations in circulating tumor cells isolated from patients with metastatic NSCLC." (PMID 23232076, 2012). "Previous studies have indicated that cytoplasmic EGFR immunostaining is associated with higher tumor stage and grade and poor prognosis in RCCs." (PMID 23202921, 2012). "The majority of p27 in tumor cells is regulated by ubiquitin degradation, and an upregulation of p27 has been associated with downregulation of skp2 via erbB-2 or EGFR inhibition." (PMID 22322523, 2012). "The rationale for treatment attempts of various tumor types with antibodies that are directed against the EGFR is based on the observation that disturbance of EGFR signaling is linked to malignant transformation and tumor progression." (PMID 23028903, 2012). "Both EGFR and KRAS mutations were found more often in ADC than in other tumor types and EGFR mutations were more common in females compared to males." (PMID 22528563, 2012). "Increased expression and/or aberrant function of EGFR are associated with tumor progression and poor prognosis in many epithelial neoplasms, including HCC." (PMID 23162604, 2012). "Epidermal growth factor receptor (EGFR) sequences were determined using tumor specimens from 58 patients, and 29 showed an EGFR mutation." (PMID 22695392, 2012). "Our data suggest its exploitation as a potential strategy for the treatment of HNSCC and other tumor entities characterized by therapy resistance linked to dysregulated EGFR activation." (PMID 22289787, 2012).
tumor (continued). "The tumor suppressor function of γ-secretase has been implicated in the mechanism that links the EGFR pathway and the Notch pathway." (PMID 23202921, 2012). "The efficacy of the association between an EGFR/HER2 mAbs with TKIs has been documented in preclinical studies in several cell lines originating from different tumour types." (PMID 23234355, 2012). "Each tumor cell is equipped with an EGFR signaling pathway linked to a cell-cycle pathway to determine its phenotype." (PMID 22935054, 2012). "Studies have found that approximately 10% to 20% of NSCLC tumours harbour somatic mutations in the EGFR gene." (PMID 22666589, 2012). "The suppression of EGFR signaling in the colon was associated with a reduction in tumor-incidence in mice fed a DHA-enriched diet." (PMID 22761867, 2012). "Previously, we had also reported several non-small cell lung cancer (NSCLC) tumour DNA samples that showed discordant results in the EGFR mutation status between HRM and Sanger sequencing." (PMID 22643842, 2012). "Clinically, HER2 and EGFR overexpression and the associated increase in cellular signal transduction is a common feature of tumours such as breast cancer and gastric cancer, and is associated with aggressive disease." (PMID 22240796, 2012). "Phosphatase and tensin homologue located on chromosome 10 deletion was also associated with EGFR protein overexpression (15 out of 42, 35.7% vs 30 out of 153, 19.6% of EGFR-negative tumours, P=0.038)." (PMID 22240798, 2012). "We used an EGFR mutation detection kit, and found 16 of 75 tumor samples were positive for EGFR mutation." (PMID 22615840, 2012). "There has also been evidence for targeting this signaling pathway from both ends, with a report showing rapamycin promotes a response to EGFR inhibitors in either PTEN-sufficient or PTEN-deficient GBM cells by reducing tumor cell growth." (PMID 22530121, 2012). "The tumor sample from 1 NSCLC patient (SD) was EGFR-WT, with a normal EGFR copy number and K-ras mutation positive." (PMID 22878519, 2012). "Most of patients with NSCLC have their tumor analyzed when the pathological diagnosis is confirmed, and the results of EGFR mutational analysis are usually available at the beginning of the first-line chemotherapy." (PMID 22613958, 2012). "We and others have previously shown that inhibition of the EGFR/Ras/PI3K/Akt pathway can increase susceptibility to radiation-induced tumor killing." (PMID 22452803, 2012). "The SUVmax was associated with multiple prognostic factors including the tumor size, LN metastasis, histologic grade, ER, PR, EGFR, Ki-67, and so on." (PMID 22741544, 2012). "As the PI3K/Akt pathway and EGFR regulate TF expression in cancer cells, targeting these signaling components is expected to potentially inhibit TF expression-associated tumor progression." (PMID 22534171, 2012). "The emergent knowledge of molecular tumor profiles e.g., EGFR and KRAS mutations and ALK rearrangements for instance raises logistic and algorithmic considerations to approaching the molecular management of the adenocarcinoma subtype of NSCLC." (PMID 25562798, 2012). "It is reported that the major mechanisms of erlotinib resistance are gatekeeper mutation (T790M) of EGFR and c-Met amplification in tumor cells." (PMID 22209766, 2012). "Our results support and underline the roles of Akt and EGFR in TF-related tumor growth and metastasis." (PMID 22534171, 2012). "Assessments included adverse events, tumor response, pharmacokinetics, pharmacodynamics, 2 [18F] fluoro-2-deoxyglucose positron-emitting tomography, and epidermal growth factor receptor and K-ras mutations." (PMID 22878519, 2012). "Each tumor cell is equipped with an EGFR signaling pathway linked to a cell-cycle to determine its phenotype." (PMID 22935054, 2012).
tumor (continued). "SUVmax were associated with numerous prognostic factors such as tumor size, LN metastasis, histologic grade, and expression levels of ER, PR, EGFR, and Ki-67 among others; these findings are similar to those reported by previous studies." (PMID 22741544, 2012). "Tumor cells over expressing the RTK EGFR are associated with poor prognosis due to phosphorylation-induced activation of AKT, STAT, and ERK pathways and to tumor cell proliferation, resistance to apoptosis, and metastasis." (PMID 23130020, 2012). "Regarding the pre-analytical phase in the study of EGFR mutations, it is important to note that macrodissection was performed on 22 of the 136 tumours analyzed (16%); 95.5% of the macrodissected samples were surgical specimens." (PMID 22952784, 2012). "Using the Therascreen EGFR Mutation Test Kit, EGFR mutations were identified in a 5% dilution of the total DNA in all of the tumours." (PMID 22952784, 2012). "In a multivariate analysis involving tumor histology, smoking status, sex, and tumor stage, EGFR mutation was an independent factor for tumor response (OR 0.18, 95% CI 0.09 to 0.38, P < 0.001)." (PMID 22901364, 2012). "EGFR mutational status obtained with direct sequencing was confirmed with the Therascreen EGFR Mutation Test Kit in 126 of the samples included in the comparative study: 18 mutated and 108 wild-type tumours." (PMID 22952784, 2012). "In summary, we demonstrated that PI3K/mTOR dual inhibitors are effective radiosensitisers in tumor cells with EGFR overexpression or oncogenic Ras mutation." (PMID 22452803, 2012). "It was recently suggested that amplification of ERBB2 comprises another resistance mechanism, and that acquired resistance is conferred by mutation of EGFR itself or results from expansion of tumor subclones with mutated or amplified KRAS." (PMID 23226389, 2012). "For example, mutations in EGFR are linked with increased activation of the epidermal growth factor receptor (EGFR) signaling pathway, which drives tumor growth and promotes survival in several types of cancer." (PMID 23284662, 2012). "Loss of PTEN expression was frequently found in tumours overexpressing EGFR (28.6%) and/or HER2 (52.6%)." (PMID 22240798, 2012). "Tumor growth suppression by PEITC treatment was associated with increased apoptosis in the tumor cells, which in turn was linked with the inhibition of EGFR and AKT activation." (PMID 22952709, 2012). "On another hand, the risk in using such an agent is its ability to activate EGFR mediated downstream signaling such as RAS-Erk required for tumor proliferation." (PMID 23144978, 2012). "Direct DNA sequencing of PCR-amplified genomic DNA has been developed to detect EGFR mutations in patient’s tumor tissue." (PMID 23232076, 2012). "For LAd, EGFR-mutant tumours showed lower risk score values, as expected due to their best clinical behavior." (PMID 22880004, 2012). "The tumor tissue was analyzed for the presence of an EGFR mutation using the PNAClampTM EGFR Mutation Detection kit (PANAGENE, INC." (PMID 22405425, 2012). "Such tumor-promoting effects of genistein are associated with increased phosphorylation of EGFR and Src tyrosine kinases." (PMID 21603581, 2011). "There was also a striking difference in PFS in patients with EGFR-mutated tumours treated with gefitinib compared with those treated with chemotherapy (9.5 vs 6.3 months; HR=0.48; P<0.001)." (PMID 21654681, 2011). "Activation of the PI3K pathway can be achieved through a number of molecular mechanisms, including loss of the PTEN tumor suppressor gene, mutation in EGFR, and amplifications of ERBB2 (HER2NEU), as well as through mutation of PIK3CA." (PMID 21303542, 2011). "From December in 2008 to November in 2010, 220 patients joined the EGFR mutation analysis using body fluids since sufficient tumor tissues were unavailable after routine pathological examination was done." (PMID 22142557, 2011).